INS (insulin)
Diseases named in the same sentence as INS in open-access papers (continued):
Sharing a sentence is not in itself a finding about the gene and the disease.
Hyperglycemia (continued). "She managed at home with once-daily insulin detemir, a low-carbohydrate diet, and intermittent corrections of hyperglycemia with IM insulin lispro." (PMID 41472947, 2026). "The optimization of insulin dosing remains a significant clinical challenge, as inappropriate dosing can lead to hypoglycemia or hyperglycemia, each carrying substantial morbidity risks." (PMID 41901583, 2026). "Insulin edema in this case likely developed as a result of relatively rapid correction of long-standing hyperglycemia after initiation of insulin therapy, although the exact glycemic trajectory before admission was unavailable." (PMID 41476905, 2026). "Chronic hyperglycaemia impairs insulin secretion by disrupting beta-cell metabolism and reducing expression of insulin." (PMID 41891907, 2026). "Along with continuous 10% dextrose fluid administration, she was started on an insulin infusion to treat persistent hyperglycemia that developed quickly after presentation." (PMID 41458137, 2026). "Rare hypoglycemia and more common hyperglycemia measurement events were counted, along with insulin administration, which was common." (PMID 41716002, 2026). "These mice are well‐established models for T2DM, characterized by hyperglycemia, lipid metabolism disorders, chronic inflammation and relatively insufficient insulin secretion." (PMID 41509193, 2026). "Treatment of diabetic Akita mice with insulin for 16 weeks normalized hyperglycemia and significantly increased renal NEP activity compared to untreated age-matched diabetic Akita mice (p < 0.05)." (PMID 41601953, 2026). "Both extracts regulate blood glucose levels, enhance insulin sensitivity, and effectively manage hyperglycemia." (PMID 41564023, 2026). "The last category is gestational diabetes mellitus (GDM), a pathological state manifested as abnormal glucose tolerance or hyperglycemia attributable to insufficient insulin production or signaling transduction in pregnant women." (PMID 41601904, 2026). "In vivo, however, GLP-1-GIP-lanifibranor outperforms GLP-1R-GIPR co-agonism and semaglutide, further decreasing body weight, food intake and hyperglycaemia in obese and insulin-resistant mice through synergistic incretin and PPAR action." (PMID 42056522, 2026). "The reason for the opposing effects of GLP-2 on insulin concentrations during hyperglycemia and hypoglycemia is unclear." (PMID 41541287, 2026). "• Correction doses can be used to manage hyperglycemia, with dosing iniated at 0.5–1 U of rapid‐acting insulin per 50 mg/dL increase in glucose levels above 150 mg/dL, adjusted according to glucose monitoring." (PMID 41552835, 2026). "Steroid-induced hyperglycemia was managed by short-acting insulin (Actrapid) and long-acting insulin (Lantus), titrated according to capillary glucose levels." (PMID 41497060, 2026). "Mean glucose level, daily insulin requirement, hypoglycemia, hyperglycemia, and glycemic variability were similar between groups (all p > 0.05)." (PMID 42197075, 2026). "Progression to abnormal glucose tolerance, as measured by oral glucose tolerance test or hemoglobin A1c, is considered stage 2, and stage 3 T1D is defined by symptomatic hyperglycemia and the need for insulin replacement therapy." (PMID 41837235, 2026). "Glibenclamide is a first‐choice treatment for managing hyperglycemia‐induced renal complications via promoting insulin secretion and reducing oxidative stress." (PMID 41583543, 2026). "Specifically, more opportunities for regulating insulin delivery during PA, and better guidance that focuses on how to avoid both hypo- and hyperglycemia in relation to PA when using HCL technology." (PMID 42129741, 2026). "Numerous studies have demonstrated that dyslipidemia in serum and metabolic tissues, such as skeletal muscle, adipose tissue, and liver, is a significant factor contributing to impaired insulin sensitivity, ultimately leading to hyperglycemia." (PMID 41509193, 2026).
Hyperglycemia (continued). "During euglycemia and hyperglycemia, bsAUC for insulin was similar during placebo and GLP-2 infusion." (PMID 41541287, 2026). "She had cachexia, acanthosis nigricans, and persistent hyperglycemia despite intravenous insulin infusion exceeding 4 units/kg/day." (PMID 42255432, 2026). "Whereas short-acting GLP1RAs suppress postprandial hyperglycemia mainly by delaying gastric emptying, long-acting GLP1RAs such as dulaglutide and liraglutide lower fasting and postprandial BS by enhancing insulin secretion and reducing glucagon secretion." (PMID 41347115, 2026). "Small increases in α-cell glucagon secretion normally occur at mealtimes, which augment insulin secretion from surrounding β cells; however, excess postprandial glucagon secretion in T2D can worsen hyperglycemia by increasing hepatic glucose production." (PMID 41502124, 2026). "It is driven by hyperglycemia, intermittent supraphysiologic insulin exposure, and enzymatic imbalances in glycogen metabolism, creating a cycle of excessive glycogen storage with inadequate degradation, leading to progressive hepatomegaly." (PMID 41560719, 2026). "It occurs when there is either an absolute or relative deficiency in insulin secretion or the inability of the body′s cells to utilize insulin effectively, which leads to hyperglycemia." (PMID 41541001, 2026). "The liver is the central organ for glucose and lipid metabolism, and impaired hepatic regulatory mechanisms lead to hyperglycemia, insulin resistance, and hepatic lipid accumulation." (PMID 42292816, 2026). "With HHS, however, hypovolemia from osmotic diuresis due to hyperglycemia is severe, but as shown in the present study, insulin secretion remains preserved to some extent, and lipolysis and ketone bodies production is limited." (PMID 41292690, 2026). "In db/db mice, PP III administration significantly reduced hyperglycemia while enhancing insulin sensitivity." (PMID 41924526, 2026). "Treatment with the insulin sensitizing agent rosiglitazone effectively ameliorated hyperglycemia, restored renal NEP expression to normal levels, and markedly reduced albuminuria in these mice." (PMID 41601953, 2026). "Suggested causes of hyperglucagonemia include decreased insulin action during diabetic ketosis (DK) and diabetic ketoacidosis (DKA) and stress from marked hyperglycemia and dehydration during a hyperosmolar hyperglycemic state (HHS)." (PMID 41292690, 2026). "Excess lipids and their metabolites (e.g., ceramides, diacylglycerols) disrupt insulin signalling pathways within hepatocytes, leading to uninhibited hepatic glucose output and exacerbating fasting hyperglycemia." (PMID 41388732, 2026). "It typically occurs with the initiation or rapid escalation in dosage of insulin, especially in patients who have experienced prolonged uncontrolled hyperglycemia." (PMID 41640926, 2026). "In beta cells, increased O-GlcNAcylation has been reported to preserve insulin secretion during hyperglycaemia, possibly through enhanced Ins1/Ins2 gene expression via epigenetic regulation." (PMID 41136741, 2026). "Secondary outcomes included quality of insulin prescriptions, hypoglycemia and hyperglycemia rates, and hospital length of stay (LOS)." (PMID 42095773, 2026). "During the experiment, insulin treatment normalized hyperglycemia in diabetic Akita mice for more than 15 weeks and significantly increased urinary expression of the full-length immunoreactive NEP band in diabetic Akita mice at 27 weeks (p < 0.05)." (PMID 41601953, 2026). "The observed Aβ dysregulation likely arises from synergistic interactions among disrupted insulin signaling, chronic hyperglycemia, and neuroinflammation." (PMID 41484634, 2026). "Management consisted of steroid withdrawal under observation, broad-spectrum antibiotics in cellulitis, hyperglycemia control with aggressive insulin, and supportive care." (PMID 41497060, 2026).
Hyperglycemia (continued). "Subcortical nuclei, including the basal forebrain (BF) and mediodorsal thalamus, play critical roles in regulating DMN-associated cognitive processes and are particularly vulnerable to hyperglycemia and brain insulin resistance." (PMID 41685355, 2026). "Capivasertib, an AKT (protein kinase B) inhibitor, in combination with fulvestrant, reduces the risk of progression in recurrent breast cancer; however, it frequently leads to hyperglycemia by disrupting the insulin signaling pathways." (PMID 42022705, 2026). "Clearly, blood glucose concentration at the time of sampling will impact C-peptide concentration: hypoglycaemia reduces, while hyperglycaemia stimulates secretion of pro-insulin." (PMID 41355468, 2026). "Green-synthesized SeNPs with Moringa oleifera have a similar impact to insulin by reducing hyperglycaemia and deactivating α-amylase and α-glucosidase." (PMID 41591058, 2026). "Consistent with previous reports, systemic improvements in hyperglycemia, insulin sensitivity, and reductions in peripheral inflammatory cytokines (e.g., TNF-α, IL-6) were observed in MSC-treated DM models." (PMID 40244194, 2025). "Pedersen proposed that maternal hyperglycemia results in fetal hyperglycemia and, consequently, hypertrophy of fetal islet tissue with insulin hypersecretion." (PMID 40729762, 2025). "This hypoglycemia is seen in 5–21% patients after cardiac surgery prompting a more conservative insulin dosing which, in turn, can result in persistent hyperglycemia." (PMID 40425725, 2025). "Chronic hyperglycaemia increases reactive oxygen species (ROS) production and overwhelms the body’s antioxidant defence mechanisms, further exacerbating insulin resistance and cellular damage." (PMID 40569910, 2025). "It is well known that induction with STZ impairs pancreatic β-cells, resulting in reduced activity and decreased insulin sensitivity, leading hyperglycemia." (PMID 39846548, 2025). "Each episode presented with dehydration, metabolic acidosis, and hyperglycemia (>500 mg/dL), necessitating intravenous insulin and fluid resuscitation." (PMID 41393705, 2025). "Two hedgehogs in this study were in a state of persistent hyperglycemia, and it was confirmed that blood glucose levels decreased in response to insulin treatment." (PMID 40427332, 2025). "Natural plant extracts and their active constituents, with potent antioxidant properties, are beneficial in reducing hyperglycaemia, enhancing insulin signalling and resistance, and promoting β cell regeneration and function." (PMID 40887321, 2025). "Preclinical studies underscore their efficacy in reducing hyperglycemia, enhancing insulin sensitivity, preserving pancreatic β-cell function, and protecting against diabetic complications, including nephropathy and cardiovascular diseases." (PMID 40843204, 2025). "Among these, skeletal muscle activity-induced BDNF secretion can enhance insulin secretion and reduce blood glucose levels during hyperglycemia]." (PMID 40933306, 2025). "Hyperglycaemia and insulin sensitivity via activation of AKT2 and AMPK were ameliorated, and the expression of GLUT4, AKT2, and AMPK, whose levels were reduced under diabetic conditions, increased." (PMID 39861420, 2025). "The reduced proteolysis of incretins by bacterial DPP-4 resulted in a decline in blood insulin levels and an increase in postprandial hyperglycemia because incretins increase insulin production from pancreatic cells after food intake." (PMID 40429343, 2025). "Delivery of TPN will be further complicated during the hypothermic conditions of an induced torpor-like state, as it can hinder insulin sensitivity and reduce insulin secretion, resulting in hyperglycaemia." (PMID 40430135, 2025). "The observed pattern provides additional evidence that maternal hyperglycemia enhances fetal insulin synthesis among GCK(-) offspring, leading to neonatal complications associated with fetal overgrowth." (PMID 40649834, 2025).
Hyperglycemia (continued). "It is characterised by hyperglycaemia, caused by defective insulin secretion, usually in type 2 DM (T2DM) failing to overcome decreased insulin sensitivity." (PMID 40480914, 2025). "Insufficient insulin results in hyperglycaemia, and individuals with T1D require multiple daily insulin injections or continuous subcutaneous insulin infusion (CSII) via an insulin pump to maintain normoglycemia." (PMID 40718205, 2025). "Effective prevention of DKA and HHS starts with structured patient education, emphasizing consistent insulin use, regular glucose monitoring, and early recognition of hyperglycemia and ketosis." (PMID 41141170, 2025). "Dolutegravir interferes with magnesium at the cellular level, causing hypomagnesemia, which results in reduced insulin secretion from the pancreas and resistance at the receptors (GLUT 4) on the target tissues; hence, hyperglycemia." (PMID 41401200, 2025). "These automated insulin delivery features help to increase CSII user safety by preventing both hypoglycaemia and hyperglycaemia through over- or under-delivery of insulin." (PMID 39496965, 2025). "In diabetic canine and mouse models, SPARC significantly reduced hyperglycemia, improved glucose tolerance, and markedly increased both pancreatic islet area and insulin secretion." (PMID 41185072, 2025). "DKA consists of a triad of hyperglycemia, metabolic acidosis, and increased blood ketones that results from inadequate insulin levels, leading to inappropriate metabolism of triglycerides and amino acids." (PMID 40978981, 2025). "Insulin is often the third line of treatment unless the patient is critically ill or during surgeries and other emergencies when hyperglycemia is uncontrollable by other antidiabetic drugs." (PMID 41214779, 2025). "A rise in plasma insulin levels activates glucose uptake and utilization in skeletal muscle, while postprandial hyperglycemia triggers the pancreas to release insulin." (PMID 40283443, 2025). "Some studies have suggested that PasiLAR-induced hyperglycemia is manageable with common antidiabetic medications such as metformin, sitagliptin, liraglutide, and insulin." (PMID 40622518, 2025). "Due to the consequential fetal hyperglycemia, insulin, glucose, and leptin signaling in the fetal brain are dysregulated." (PMID 40077761, 2025). "Surprisingly, she showed a significant reduction in insulin requirement via the IV route to control her hyperglycemia (less than 1 unit/kg/day of IV insulin within 2–3 h of treatment)." (PMID 41424588, 2025). "Advances in stem cell research have enabled the generation of functional pancreatic cells from PSCs, which can secrete insulin in response to glucose, potentially reversing hyperglycemia." (PMID 40046060, 2025). "The ADJUNCT ONE and TWO trials found similar results in terms of body weight and insulin reduction with the 1.8 mg dose of liraglutide, but with an additional modest decrease in HbA1c, as well as an increase in hypoglycemia and hyperglycemia with ketosis." (PMID 40707821, 2025). "Reduced insulin secretion results in hyperglycemia, which contributes to β cell failure in a vicious cycle." (PMID 40512624, 2025). "Previously, cats fed a high-carbohydrate diet (NFE = 47% ME) exhibited prolonged hyperglycemia following a meal-test, suggestive of alterations in insulin sensitivity." (PMID 40052519, 2025). "Key metrics included time in the target glucose range (3–10 mmol/L), percentage of time spent in hypoglycemia (<3 mmol/L), and hyperglycemia (>10 mmol/L), alongside insulin dosage requirements." (PMID 41332894, 2025). "RC, known for its strong atherogenic potential, can lead to reduced blood flow and compromised pancreatic function, ultimately resulting in decreased insulin secretion and hyperglycemia." (PMID 39508748, 2025). "The significant delay period from normal insulin injection to peak insulin absorption and concentration results in postprandial hyperglycemia." (PMID 40137145, 2025).
Hyperglycemia (continued). "Conversely, βNrf2KO mice displayed reduced plasma insulin levels, hyperglycemia and decreased glucose tolerance during pregnancy." (PMID 40054060, 2025). "Insufficient insulin secretion or insulin resistance (IR) compromises this regulation, leading to chronic hyperglycemia and metabolic dysregulation." (PMID 41035908, 2025). "AMPK activity is decreased during many pathological conditions, including resistance to insulin, hyperglycemia, obesity, Alzheimer’s, and cancer." (PMID 40438603, 2025). "Early hyperglycemia due to ischemia–reperfusion injury decreased to normal levels with insulin supplementation, demonstrating an active liver hormonal response." (PMID 40026238, 2025). "Specifically, administration of dihydromyricetin (6 g/kg) alleviates high-fat diet-induced IR and abnormal insulin secretion, improving hyperglycemia by activating ILC3 cells." (PMID 39963239, 2025). "Under physiological conditions, postprandial hyperglycemia stimulates pulsatile insulin secretion, facilitating glucose uptake in peripheral tissues, while fasting glucose levels are maintained through glucagon‐mediated hepatic glucose output." (PMID 41426511, 2025). "We have observed here that 2 copies of the HbS gene promote early onset hyperglycemia, seen as early as 8 weeks of age—the first analysis time point—in the presence of comparable fasting insulin levels as SCT and littermate control mice." (PMID 40294908, 2025). "First, the intrinsic design of AID algorithms often results in more frequent corrective boluses and intensified insulin delivery, particularly to minimize postprandial hyperglycemia." (PMID 41010993, 2025). "Nevertheless, morin was proven to ameliorate the hyperglycemia and insulin sensitivity attributed to the repression of PERK-adjusted transporter degradation and the boosted expression of glucose transporter proteins in both HepG2 cells and diabetic rats." (PMID 40298635, 2025). "The resulting chronic ER stress and impaired insulin secretion contribute to the clinical manifestations of MODY10, which range from neonatal diabetes (severe mutations like R6C) to adult-onset hyperglycemia (milder variants like G32S)." (PMID 40869431, 2025). "The primary mechanisms involve decreased insulin secretion and resistance, and prolonged hyperglycemia induces oxidative stress that damages cells and leads to apoptosis of enteric neurons." (PMID 41195415, 2025). "Slc30a8 knockout mice display conflicting phenotypes across studies, ranging from hyperglycaemia and impaired insulin secretion to protection against cytokine-induced stress and hypoxia." (PMID 40768044, 2025). "Inaccurate results can influence therapeutic decision-making regarding insulin dosage and can therefore be of clinical relevance while worsening hypo- or hyperglycemia." (PMID 40248187, 2025). "It is characterized by impaired glucose tolerance due to an increase in anti-insulin substances and decreased insulin sensitivity, leading to hyperglycemia and other metabolic disturbances." (PMID 40958678, 2025). "The Gnasβcell–/– mice described here have low and unchanging levels of circulating insulin and develop severe hyperglycemia." (PMID 40526441, 2025). "These cases also showed hyperglycemia (blood glucose levels of 304-593 mg/dL), low HbA1c levels (5.5%-7.6%), and insulin secretory defect at onset." (PMID 40406776, 2025). "Glucose is transferred through the placenta via facilitated diffusion, meaning that maternal hyperglycemia related to GDM leads to fetal hyperglycemia, which, in turn, stimulates greater fetal insulin production and results in fetal hyperinsulinemia." (PMID 41018546, 2025). "Other authors have indicated that administering an additional insulin dose with protein- and fat-containing meals helps prevent postprandial hyperglycemia." (PMID 41156539, 2025).